NRAS (NRAS proto-oncogene, GTPase)
Diseases named in the same sentence as NRAS in open-access papers (continued):
Sharing a sentence is not in itself a finding about the gene and the disease.
metastatic colorectal cancer (68 papers, 2013 to 2026). "KRAS mutations are present in approximately 35–45% of metastatic colorectal cancer cases, with NRAS mutations occurring in a smaller subset." (PMID 40805233, 2025). "This study aimed to evaluate KRAS and NRAS mutations over an eight-year period to provide a comprehensive understanding of the genetic landscape of metastatic colorectal cancer (mCRC) in Turkish patients." (PMID 40411151, 2025). "Determining the RAS (KRAS/NRAS) mutational status on a tumor biopsy is mandatory to guide the best treatment recommendation in metastatic colorectal cancer (mCRC)." (PMID 38642257, 2024). "RAS (KRAS/NRAS) mutational status on a tumor biopsy is mandatory to guide the best treatment in metastatic colorectal cancer (mCRC)." (PMID 38642257, 2024). "Although approximately half of all metastatic colorectal cancers (mCRCs) harbour mutations in KRAS or NRAS, hardly any progress has been made regarding targeted treatment for this group over the last few years." (PMID 37604687, 2023). "The aim of this study is to report the largest North African description of KRAS and NRAS status in metastatic colorectal cancer and to describe the association of these mutations with clinicopathological characteristics." (PMID 37277698, 2023). "This study evaluated the role of NRAS mutations as a prognostic marker in metastatic colorectal cancer (mCRC), among 786 patients treated at the University Hospital of Pisa from 2009 to 2012." (PMID 35546237, 2022). "The Idylla© Biocartis, a fully automated real-time-PCR-based molecular diagnostic system, was used in a patient with metastatic colorectal cancer with a NRAS mutation in progression after several therapeutic lines." (PMID 35611253, 2022). "KRAS and NRAS mutations are identified resistance mutations to anti-epidermal growth factor receptor monoclonal antibodies in patients with metastatic colorectal cancer." (PMID 30811471, 2019). "It is well known that activating mutations in the KRAS and NRAS genes are associated with poor response to anti-EGFR therapies in patients with metastatic colorectal cancer (mCRC)." (PMID 30344942, 2018). "The third case (P0025) is also a metastatic colorectal cancer with an activating mutation in NRAS (p.Q61R), predicting insensitivity to cetuximab/panitumumab." (PMID 27245685, 2016). "By extension, it is reasonable to surmise that patients with dMMR/MSI-H metastatic colorectal cancer harboring a KRAS or NRAS mutation may be more likely to recur if immunotherapy is stopped." (PMID 38085001, 2023). "Background/Objective: The prognostic value of specific hot-spot mutations within KRAS, NRAS, and BRAF genes in metastatic colorectal cancer (mCRC) genes remains debatable." (PMID 40075837, 2025). "For 50% of patients with KRAS/NRAS/BRAF wild-type metastatic colorectal cancer, the median survival after treatment is approximately 30 months." (PMID 38576495, 2024). "Approximately 50% of patients with metastatic colorectal cancer has mutations in the RAS gene, including HRAS, KRAS, and NRAS mutations, most of which are KRAS mutations." (PMID 37370699, 2023). "This study aimed to evaluate its safety, tolerability, pharmacokinetics (PK), and efficacy in patients with wild-type KRAS/NRAS/BRAF metastatic colorectal cancer (mCRC)." (PMID 36307775, 2022). "Whereas, in metastatic colorectal cancer, BRAF mutation seems to have the poorest prognosis compared with KRAS and NRAS." (PMID 34063325, 2021). "Metastatic colorectal cancer (mCRC) harbors several mutations with different prognostic and predictive values; KRAS, NRAS, and BRAF mutations are the best known." (PMID 34988329, 2021). "Mutations in KRAS, NRAS, and BRAF (RAS/BRAF) genes are the main predictive biomarkers for the response to anti-EGFR monoclonal antibodies (MAbs) targeted therapy in metastatic colorectal cancer (mCRC)." (PMID 32628708, 2020).
metastatic colorectal cancer (continued). "We evaluated the ability of the fully-automated molecular diagnostics platform Idylla for the detection of KRAS, NRAS and BRAF hotspot mutations in plasma from patients with metastatic colorectal cancer (mCRC)." (PMID 31940389, 2020). "A total of 779 FFPE samples from patients with metastatic colorectal cancer with valid NGS results were screened and 22 uncommon mutational profiles of KRAS, NRAS and BRAF genes were selected." (PMID 31068650, 2019). "This study suggests that Jordanian patients with metastatic colorectal cancer have a higher rate of KRAS outside exon 2 and NRAS mutations when compared to the literature." (PMID 31881025, 2019). "We assessed 72 consecutive patients with a diagnosis of metastatic colorectal cancer (mCRC) using IdyllaTM Biocartis, a fully automated platform that evaluates the most frequent mutations of KRAS, NRAS and BRAF genes." (PMID 31597339, 2019). "Assessment of KRAS, NRAS (RAS) and BRAF mutations is a standard in the management of patients with metastatic colorectal cancer (mCRC)." (PMID 31265477, 2019). "The most common mutations in KRAS, NRAS and BRAF genes were detected in less than 90 minutes in tissue biopsies and plasma samples of metastatic colorectal cancer patients." (PMID 30562355, 2018). "The aim of this study was to investigate the efficacy and safety of first-line panitumumab plus folinic acid, 5-fluorouracil and irinotecan (FOLFIRI) in patients with wild-type KRAS and wild-type NRAS metastatic colorectal cancer (mCRC)." (PMID 29587749, 2018). "International guidelines made RAS (KRAS and NRAS) status a prerequisite for the use of anti-EGFR agents for metastatic colorectal cancer (CRC) patients." (PMID 29755687, 2018). "In 2014 the European Medicines Agency included exon 2, 3 and 4 KRAS and NRAS testing for the selection of metastatic colorectal cancer (mCRC) patients eligible for the therapy with anti-EGFR monoclonal antibodies." (PMID 26335936, 2015). "This evidence was rapidly followed by a directive of the European Medicines Agency (EMA) that restricted the use of panitumumab (Vectibix®) and cetuximab (Erbitux®) to patients with KRAS and NRAS (exon 2, 3 and 4) wild type metastatic colorectal cancer." (PMID 26435479, 2015). "This study aimed to integrate gene alterations associated with predictive and prognostic outcomes in patients with metastatic colorectal cancer (mCRC) with polymerase chain reaction (PCR) and in-house next-generation sequencing (NGS) to detect KRAS, NRAS, and BRAF mutations." (PMID 35723364, 2022). "Another recent study aimed to determine how KRAS, NRAS and BRAF mutations in hematopoietic cells may alter the results of liquid biopsies in patients with metastatic colorectal cancer." (PMID 35127745, 2021). "Given that metastatic colorectal cancer (mCRC) patients underwent genomic profiling for clinically actionable mutations such as KRAS, NRAS, and BRAF analysis routinely with a clinically validated COBAS panel, we rationalized separating this cohort from the remaining patients." (PMID 33014822, 2020). "Mutations in KRAS and NRAS genes are negative predictors of anti-EGFR therapies response in metastatic colorectal cancer." (PMID 25859555, 2015). "The clinical implication of this association is unclear, as NRAS mutations in metastatic colorectal cancer have not been associated with relevant clinical or pathologic features in prior population-based studies among patients treated with oxaliplatin." (PMID 25208577, 2014). "In addition, NRAS activating mutations, amplification or upregulation have been implicated in resistance to targeted therapies such as TKIs used in NB and other cancers, such as hepatocellular carcinoma (HCC), metastatic colorectal cancer and NSCLC74–77." (PMID 38653965, 2024).
metastatic colorectal cancer (continued). "BRAF and KRAS mutations have been reported to occur in ∼10% and 44% of patients with metastatic colorectal cancer, which is similar to frequency (KRAS: 46%; BRAF: 11.2%; NRAS: 3%) observed in our sample cohort." (PMID 37483495, 2023). "The aim of this study was to investigate the effects of baseline plasma AREG levels in KRAS, NRAS, and BRAF wild-type metastatic colorectal cancer (CRC) on treatment outcome with palliative first-line cetuximab + FOLFIRI chemotherapy." (PMID 34893673, 2021). "This all-in-one strategy is particularly relevant for metastatic colorectal cancer cases whose MSI status contributes to tumour prognosis and patient selection for immunotherapy while KRAS, NRAS and BRAF genotyping helps for targeted therapies decision." (PMID 33009475, 2020). "A relevant role for NGS is the prediction of response to anti-EGFR agents in metastatic colorectal cancer (mCRC), where multiple exons from KRAS, NRAS, and BRAF must be sequenced simultaneously." (PMID 31036005, 2019). "Cetuximab is approved for the treatment of metastatic colorectal cancer but its response rate in KRAS, BRAF, NRAS and PIK3CA exon 20 quadruple wild-type tumors accounts for only 41%, leaving a high percentage of non-responders." (PMID 28032592, 2017). "However, in a larger set at our institution of 246 patients with metastatic colorectal cancer with only mutation data available, a pattern of dual NRAS/CTTNB1 mutations could not be confirmed." (PMID 25208577, 2014). "Similarly, in metastatic colorectal cancer, biomarker testing for KRAS/NRAS, BRAF V600E, MSI, HER2, and NTRK fusions is essential for selecting systemic therapy and clinical trials." (PMID 41462880, 2025). "National and European guidelines recommend a first-line doublet or triplet chemotherapy regimen as induction therapy associated with targeted therapy depending on the KRAS, NRAS and BRAF status for patients with pMMR/MSS non-resectable metastatic colorectal cancer." (PMID 39796718, 2024).
myeloma (51 papers, 2010 to 2025). "Clinical and laboratory characteristics of patients with plasma cell myeloma according to KRAS/NRAS/BRAF mutation status." (PMID 37212518, 2023). "In this study, our goal is to assess the clinical implications of KRAS/NRAS/BRAF mutations in myeloma patients, as these mutations have potential implications for targeted therapy." (PMID 37212518, 2023). "We therefore systematically analyzed the clinicopathologic, cytogenetic, and molecular genetic features as well as OS in a large group of myeloma patients with KRAS/NRAS/BRAF mutations." (PMID 37212518, 2023). "Others have shown that myeloma is driven by mutations in the RAS signaling pathway, and that KRAS/NRAS mutations are present in 20%–50% and 45%–80% of newly diagnosed and relapsed/refractory myeloma cases, respectively." (PMID 37212518, 2023). "RAS pathway hyperactivation is a common molecular event in progressive myeloma, with almost 75% of drug-refractory myeloma patients harboring mutations in NRAS, KRAS, or BRAF2." (PMID 35739276, 2022). "Mutations of NRAS have earlier been shown to be significantly associated with lower single-agent PI-sensitivity and shorter time to progression in bortezomib-treated myeloma patients." (PMID 35264575, 2022). "By comparing these results to newly diagnosed myeloma (MM) we show fewer NRAS and FAM46C mutations together with fewer adverse translocations, del(1p), del(14q), del(16q), and del(17p) in SMM consistent with their role as drivers of the transition to MM." (PMID 33436579, 2021). "In the present study, TAK-580 specifically inhibited the RAS-RAF-MEK-ERK pathway and significantly induced anti-myeloma effects and apoptosis in NRAS-mutated INA-6 and KRAS-mutated RPMI-8226 MM cell lines." (PMID 33216827, 2020). "We found an overlap of mutations in KRAS and NRAS genes activating mitogen-activated protein kinase signaling in 5/54 myeloma patients (9.3%), most likely in different tumor subclones because of different percentages of mutant reads." (PMID 28234344, 2017). "KRAS and NRAS exon 3 mutations were significantly associated with the myeloma cohort compared with non-myeloma plasma cell dyscrasias (odds ratio (OR) 9.87, 95% confidence interval (CI) 1.07–90.72, P=0.043 and OR 7.03, 95% CI 1.49–33.26, P=0.014)." (PMID 28234344, 2017). "Mutation analysis revealed NRAS as the most commonly mutated gene (30%, 7/23) in myeloma patients followed by KRAS (26%, 6/23) and BRAF (22%, 5/23)." (PMID 27634910, 2016). "Mutation analysis of all myeloma patients including the six patients with AL amyloidosis revealed NRAS as the most commonly mutated gene (30%, 7/23), followed by KRAS (26%, 6/23) and BRAF (22%, 5/23)." (PMID 27634910, 2016). "Furthermore, multiple in vitro and in vivo evidences has shown that NRAS mutated myeloma and/or leukemic cells are resistant to KRASG12C-targeted small molecules, indicating the specificity of NRAS targeting." (PMID 35211470, 2022). "Moreover, it was found that NRAS mutations are prominent in hematopoietic and skin (melanocyte) malignancies and myelomas." (PMID 35409064, 2022). "The most frequent mutations involve KRAS and NRAS genes in multiple myeloma." (PMID 34017329, 2021). "Patients with RAS mutations have significantly shorter overall survival (OS) and progression-free survival, indicating that RAS mutations are an independent prognostic factor in MM, and NRAS mutations significantly decrease the sensitivity of myeloma to single-agent BTZ therapy." (PMID 33216827, 2020). "Notably, 6 of the 23 myeloma patients showed multi-site and/or multi-gene mutations in NRAS, KRAS, or BRAF, indicating compound aberrations in the Mitogen activated protein kinase (MAPK) pathway." (PMID 27634910, 2016). "Multiple myeloma (MM) was characterized by frequent mutations in KRAS/NRAS/BRAF within the EGFR pathway that could induce resistance to EGFR inhibitors." (PMID 25894462, 2015).
myeloma (continued). "Importantly, NRAS mutation significantly reduces myeloma sensitivity to single-agent BTZ therapy." (PMID 33216827, 2020). "Mutations in the RAS‐MAPK pathway, such as KRAS, NRAS, and BRAF, are known as high‐risk factors associated with poor prognosis in patients with various cancers, but studies in myeloma have yielded mixed results." (PMID 37212518, 2023). "In multiple myeloma, however, activating KRAS and NRAS mutations produce distinct expression signatures, necessitating separate classifiers." (PMID 35761387, 2022). "Agents targeting the RAS/MAPK pathway are well-positioned for clinical investigation given the frequency of NRAS and KRAS mutations in multiple myeloma and early examples of single agent and combination activity." (PMID 35127532, 2021). "Cobimetinib in combination with ixazomib and pomalidomide is also being further investigated in the MYDRUG umbrella protocol in NRAS, KRAS, and BRAF-mutated myeloma." (PMID 35127532, 2021). "In our cohort, 46 patients were treated with at least 1 cycle of anti-myeloma treatment and 20 of them had BRAF, KRAS and NRAS mutations." (PMID 32284750, 2020). "While there is an option to add in steroids, two myeloma patients had received RO5126766 alone, of which one of them (carrying both NRAS and KRAS mutations) achieved a partial response." (PMID 32228485, 2020). "In general, the importance of MAP kinase signaling in PC biology is suggested by the recurrent mutations of NRAS, KRAS, and BRAF in myeloma." (PMID 30642980, 2019). "In this study, we identified mutations in three well-known oncogenes, KRAS, NRAS, and BRAF, in multiple myeloma patients." (PMID 27634910, 2016). "We therefore tended to study the metabolic shift in myeloma cells with KRAS/NRAS/BRAF WT background in response to EGFR inhibition, which was expected to confer primary efficacy." (PMID 25894462, 2015). "During Step two of myeloma pathogenesis, c-Myc, NF-κB, TLR, KRAS, NRAS, and many other mechanisms that play a key role in the myeloma initiation step continue to promote myeloma cell proliferation and expansion." (PMID 24252328, 2013). "Thus, the application of a targeted gene sequencing panel in myeloma patients identified mutations in mitogen activated protein kinase (MAPK) pathway-related genes (KRAS, NRAS, and BRAF)." (PMID 27634910, 2016). "Unlike other malignancies, mutations of KRAS and NRAS were found in approximately equal rates in myeloma." (PMID 27634910, 2016). "This may be due to either functional differences between KRAS and NRAS as oncogenic drivers or the different biology of myeloma compared to solid tumors." (PMID 26709701, 2015). "Recent clinical data in multiple myeloma patients presents an interesting case, where NRAS but not KRAS mutations were associated with lower response to single-agent bortezomib." (PMID 26709701, 2015). "In multiple myeloma the mutational profile is mainly represented by translocations involving chromosome 14 and by single nucleotide mutations, frequently involving genes implicated in the mitogen activated protein kinase (MAPK) pathway, as KRAS, NRAS, and, less frequently, BRAF." (PMID 31709194, 2019).
myeloma (continued). "Conversely, methylation-mediated silencing of miR-340-5p enhanced myeloma plasma cell proliferation via upregulation of CCND1 and MAPK signaling (NRAS/MEKK1/MEKKK3/p-ERK) in addition to enhancing myeloma cell survival by targeting XIAP." (PMID 31064412, 2019). "Beyond well-known myeloma genes such as KRAS, NRAS, DIS3, and FAM46C5–8, several other interesting candidate genes emerged." (PMID 31444325, 2019). "We report here a hybrid-capture-based Liquid Biopsy Sequencing (LB-Seq) method used to sequence all protein-coding exons of KRAS, NRAS, BRAF, EGFR and PIK3CA in 64 cfDNA specimens from 53 myeloma patients to >20,000 × median coverage." (PMID 28492226, 2017). "In this study, our results suggested that both the myeloma cell lines, 8226 (KRAS G12A) and H929 (NRAS G13D), are sensitive to SHP2 inhibitors, the latter of which contradicts previous reports that RAS G13D–mutated cancer cells are resistant to SHP2 inhibition." (PMID 35462913, 2022). "Interestingly, it has been shown that mutated forms of BRAF, NRAS, and KRAS can upregulate non-constitutive proteasome expression and reduce endoplasmic reticulum stress in multiple myeloma." (PMID 38774235, 2024).